IL6 (interleukin 6)
Diseases named in the same sentence as IL6 in open-access papers (continued):
Sharing a sentence is not in itself a finding about the gene and the disease.
Hepatic steatosis (continued). "In the liver, antibody blockade of IL-6 signaling led to enhanced hepatic steatosis in response to MCD diet." (PMID 34977118, 2021). "Patients with steatosis show the highest TNF‐α and IL‐6 levels, indicating that there is an inflammation during hepatic steatosis." (PMID 34760237, 2021). "IL-6 can regulate the development of tumors by promoting the expression of specific miRNAs, and miRNAs can improve hepatic steatosis and injury by inhibiting the expression of FABP1." (PMID 34056002, 2021). "In rats with fatty liver disease, serum levels of IL-6 increased significantly, but were decreased following lycopene treatment." (PMID 34909658, 2021). "Hepatic macrophages participate in the development of fatty liver disease by secreting multiple pro-inflammatory cytokines, including IL-1β, IL-6, and TNF-α." (PMID 34956171, 2021). "It is reported that the anti-inflammatory effect of bilirubin plays an important role in reducing the production of proinflammatory cytokines (such as interleukin-6 and interleukin-1), which are involved in hepatic steatosis." (PMID 33204721, 2020). "It is well-recognized that IL6 is an important inflammatory cytokine in the development of fatty liver through the activation of the GP130-STAT3 axis." (PMID 33282902, 2020). "Numerous factors such as leptin, TNF-α, and IL-6 are involved in the initiation and progression of hepatic steatosis and related metabolic dysfunction." (PMID 32528465, 2020). "Hepatic steatosis was similarly allied with an obvious rise in the inflammatory indices evidenced by hepatic NF-κB and IL-6 by about 4.2 folds (253.2 ± 17.1 pg/ml vs. 59.6 ± 1.6 pg/ml) and 2.3 folds (784.6 ± 12.23 pg/ml vs. 329.6 ± 7.2 pg/ml), respectively." (PMID 32420546, 2020). "Hepatic steatosis is enhanced by IL-6 pathway neutralization with tocilizumab (a specific antibody against the IL-6 receptor), but improved liver damage in mice with methionine choline-deficient (MCD) diet-induced NASH." (PMID 32774420, 2020). "To directy link WAT browning to the development of hepatic steatosis after a burn injury, we sought to block the two main regulators, IL-6 and UCP-1, involved in post-burn WAT browning." (PMID 31740668, 2019). "Lower values of weight gain, AST, IL-6, and hepatic steatosis were directly correlated with the increase in PUFAs in the diets, and especial n-3 PUFA ALA, which was the major lipid source in the LO diet." (PMID 31861497, 2019). "Evaluating spleen volume by ultrasound, NASH patients showed higher values of spleen longitudinal diameter (SLD) as well as significantly higher IL-6 and vascular endothelial growth factor concentrations than in the benign form of steatosis, i.e., fatty liver." (PMID 31861591, 2019). "In our study, chronic vitamin D treatment decrease hepatic steatosis by suppressing the levels of TNFα, NFκB and IL-6 in NASH rat livers." (PMID 29684027, 2018). "These cytokines are well known mediators for inflammation or HCC induced by hepatic steatosis, because IL-6 is involved in low-grade chronic inflammation and poor prognosis of NAFLD42,43." (PMID 30356113, 2018). "Both in vivo and in vitro studies have reported that TNFα and IL-6 can exacerbate hepatic steatosis." (PMID 29684027, 2018). "In conclusion, here we described for the first time an integrated signaling module that links liver steatosis and the activation of IL6/STAT3 signaling with downstream STAT3-dependent activation of a number of miRNAs, including the onco-mir miR-21." (PMID 30206377, 2018). "Chronic exposure to IL-6 led to liver injury, although studies have concluded that it has a protective role against the progression of hepatic steatosis, and paradoxically, a hepatocytes protective role in advanced stages of NAFLD." (PMID 28388904, 2017). "Our finding that fatty liver was associated with higher TNFαR2 and IL-6 and lower adiponectin levels among HIV-uninfected men is consistent with the current understanding of fatty liver disease pathophysiology." (PMID 28929125, 2017).
Hepatic steatosis (continued). "Deletions of C536 and C1q39 also alleviate hepatic steatosis and suppress the expression of inflammatory factors (TNFα and IL6) induced by alcohol." (PMID 27550859, 2016). "Reportedly, anti-inflammatory effects of bilirubin played vital roles in reducing pro-inflammatory cytokines production, such as interleukin-6, interleukin-1, which had been found to contribute to hepatic steatosis in the murine model of NAFLD47." (PMID 27484402, 2016). "Previous studies have shown a beneficial role of IL-6 against several models of fatty liver, including alcohol liver disease." (PMID 27333268, 2016). "In agreement, previous studies have reported the exacerbation of steatosis by blocking IL-6 signaling in mice, whereas the administration of IL-6 alleviated hepatic steatosis, in part from an increase in mitochondrial β-oxidation of fatty acids." (PMID 26035386, 2015). "Especially, TNF-α mediates the early stage of fatty liver disease as well as the transition to a more advanced stage of liver disease, and stimulates the release of cytokines such as IL-4 and IL-6." (PMID 26375281, 2015). "In vitro, fructose treatment attenuated the expression of key pro-inflammatory cytokines (TNF-α and IL-6) in hepatocytes, which might contribute to the relatively low-grade inflammation in goose fatty liver despite severe steatosis." (PMID 41378259, 2025). "Furthermore, inflammatory cytokines (e.g., TNF-α and IL-6) impair insulin signaling, leading to insulin resistance, which stimulates liver fat synthesis and inhibits fat degradation, exacerbating liver steatosis." (PMID 40746546, 2025). "Resveratrol significantly lowers liver MDA levels, increases antioxidant status, and reduces hepatic IL6 levels, these biochemical changes correlate with the histopathological improvements observed, including reduced hepatic steatosis, inflammation, and fibrosis." (PMID 39859121, 2025). "Indeed, deletion of Apoa5 in hamsters led to hepatic steatosis even on a chow diet, and Apoa5 knockdown in mice resulted in increased cytokine markers of systemic inflammation, including IL-10, IL-6, and TNF-α." (PMID 41043689, 2025). "Chitin oligosaccharides can increase SCFAs content, reduce serum LPS, improve blood lipid profiles and liver steatosis, decrease the levels of inflammatory factors such as IL-1β, IL-6, and TNF-α to alleviate inflammation, and promote mRNA expression of TJPs to enhance the integrity of the IMB." (PMID 40862134, 2025). "In summary, our data indicate that KD feeding induces fibrosis and MASH through upregulated Il-6, Tnf, and Mapk13 pathways at TN, whereas adipocyte-specific gp130 deletion prevents KD-induced hepatic steatosis through reduced p-HSL, p-JNK, and p-p38 MAPK signaling." (PMID 40864559, 2025). "First, hepatic steatosis induces chronic low-grade inflammation, characterized by elevated inflammatory cytokines (e.g., IL-6, TNF-α) and C-reactive protein (CRP), which can affect the central nervous system by altering neurotransmitter metabolism and impairing mood regulation." (PMID 41011102, 2025). "We measured changes in hepatic steatosis, non-invasive fibrosis scores, inflammatory markers (including interleukin-6, tumor necrosis factor-alpha, and highly sensitive C-reactive protein), liver enzymes, and lipid profiles at baseline and at the end of the 24 weeks." (PMID 41011150, 2025). "Moreover, we aim to investigate the role of IL-6-gp130 signaling in KD-induced hepatic steatosis and glucose intolerance using liver and adipocyte-specific gp130 knockout mice." (PMID 40864559, 2025). "Adipose tissues also produce proinflammatory cytokines such as tumor necrosis factor-alpha (TNF-α), whose levels are higher in MASH compared to hepatic steatosis, and interleukin-6 (IL-6), which promotes the development of HCC by inhibiting apoptosis and activating pro-oncogenic pathways." (PMID 40560451, 2025).
Hepatic steatosis (continued). "Chronic systemic inflammation, characteristic of IBD, may contribute to hepatic lipid accumulation through inflammatory cytokines such as tumor necrosis factor-alpha and interleukin-6, which interfere with insulin signaling and promote hepatic steatosis." (PMID 41416325, 2025). "While prior work has also implicated inflammasome activation in the development or hepatic steatosis, our findings do not suggest systemic measures of IL-6, IL-18, TNF-α are associated with greater hepatic fat deposition." (PMID 40700400, 2025). "HC has been documented to induce fatty liver disease, while high-galactose consumption is associated with severe oxidative stress, senescence, and efflux of pro-inflammatory cytokines, such as TNF-α, IL-6, and IL-10, in the liver." (PMID 41462653, 2025). "All groups receiving silymarin showed a decrease in liver malondialdehyde content, expression of fatty acid synthase, tumour necrosis factor alpha, interleukin 6 (IL‐6) genes in the liver, and hepatic steatosis than the control, except those fed the PSM100 diet." (PMID 39324876, 2024). "Another study showed that synergistic treatment of Bilophila wadsworthia promoted high-fat diet (HFD)-induced local and systemic inflammation (upregulation of interferon-gamma or IFN-γ and IL-6), intestinal barrier interruption, BA and glucose metabolism dysregulation, and hepatic steatosis." (PMID 38283696, 2024). "Chronic high-dose IL6 (μg/g range), for example, reduced steatosis in 3 fatty liver disease models." (PMID 39261648, 2024). "However, compared to the BOC Sciences policosanol, Raydel® policosanol showed significantly higher efficacy in preventing HCD-provoked fatty liver changes and IL-6 generation." (PMID 39204207, 2024). "In addition, CNB-001 ameliorated hepatic steatosis while decreasing serum triglyceride and interleukin 6 (IL-6) levels." (PMID 37762669, 2023). "Additionally, the PPARγ coactivator 1 α (Pgc-1α), interleukin-6 (Il-6), and interleukin-10 (Il-10) gene expression were augmented, while hepatic steatosis decreased and liver parenchyma was recovered." (PMID 35326098, 2022). "Moreover, the HFHSD triggered hepatic steatosis, as evidenced by an increase in the inflammatory tone (assessed by IL-6 quantification) and higher hepatic weight due to triglycerides accumulation." (PMID 35276798, 2022). "In addition, at the molecular level, we detected significantly changed expression of the Pparγ (downregulation) and Il-6 (upregulation) genes, both of which are involved in the regulation of lipid metabolism and the pathogenesis of hepatic steatosis." (PMID 36013467, 2022). "In fatty liver rat models of IRI, treatment with IL-6 for 10 days before the induced liver injury could ease the hepatic steatosis and IRI." (PMID 33484391, 2021). "Hepatoprotective IL-6 and irisin are further reported to improve hepatic steatosis." (PMID 33536048, 2021). "With respect to inhibiting the inflammatory response and oxidative stress, genistein was reported to ameliorate fatty liver in insulin-resistant rats by activating the antioxidant profile, decreasing IL6 and TNF-α concentrations and preventing oxidative damage." (PMID 33953784, 2021). "Fatty liver disease is another fibrotic condition that is exacerbated by IL-6." (PMID 34909658, 2021). "The promotion of hepatic steatosis resulting from perforin deficiency was associated with a strong increase in hepatic macrophage accumulation and inflammation as evaluated by the expression of TNF-α, IL-6, and iNOS." (PMID 32528465, 2020). "Furthermore, rodent studies have revealed the critical role of cytokines such as IL6 and macrophages in activating WAT browning and causing hepatic steatosis post burn injury." (PMID 33251224, 2020). "Experimental studies suggest that both IL-6 and Irisin might be involved in muscle/liver crosstalk mediating improvement of hepatic steatosis." (PMID 33396267, 2020).
Hepatic steatosis (continued). "Our first major finding was that higher levels of proinflammatory biomarkers (ICAM-1, CRP, IL-6, and TNFαR2) and lower levels of the anti-inflammatory adiponectin were associated with fatty liver among HIV-uninfected men independent of VAT." (PMID 28929125, 2017). "The biomarkers that we found to be independently associated with fatty liver, lower adiponectin, and higher ICAM-1, CRP, IL-6, and TNFαR2 are also predictive of cardiovascular events, suggesting a potential explanation for a direct link between fatty liver and cardiovascular events." (PMID 28929125, 2017). "In addition, elevated levels of TNF-α, IL-6 and MCP-1 were associated with the development of NAFLD, and pharmacological and genetic inhibition of these pro-inflammatory mediators ameliorated hepatic steatosis in obese animals." (PMID 27213439, 2016). "A previous study indicated that fish oil could reduce ethanol-induced fatty liver and hepatic production of the inflammatory cytokines, IL-6 and TNF-α, consistent with the reduction of IL-6 having a protective effect against ethanol-induced hepatic steatosis." (PMID 27143963, 2016). "Thus, the prolonged effect of IL-6 on AMPK needs to be investigated further in hepatic steatosis models." (PMID 26077338, 2015). "Because IL-6 is also involved in hepatic triglyceride secretion, we hypothesized that the increase in IL-6 could have contributed to the improvement of hepatic steatosis by regulating hepatic fatty acid export by the liver." (PMID 21980496, 2011). "Consistently, excessive lipid accumulation could further promote TLR4/NF‐κB signaling to trigger the leakage of proinflammatory cytokines (TNF‐α, IL‐6, IL‐1β, and IL‐18), thus exacerbating the vicious cycle of inflammatory responses in the liver to aggravate fatty liver progression." (PMID 40501499, 2025). "In addition, DCA and LCA were reported to potentially increase gut permeability and increase the exposure of the liver to gut-derived toxins, which can increase proinflammatory cytokines (TNF-α and IL-6), thereby promoting inflammation and hepatic steatosis in animal models of NAFLD." (PMID 37202792, 2023). "And the associations of CRP, IL-1β, and IL-6 with hepatic steatosis were not significant." (PMID 35603224, 2022). "Studies suggest the actuation of IL-6 in inflammation, mainly concerning hypertriglyceridemia associated with visceral obesity, increases insulin resistance and accumulation of hepatic fat, characteristic of non-alcoholic fatty liver disease (NAFLD) or hepatic steatosis." (PMID 31861497, 2019). "Although our study is cross-sectional and therefore we cannot assess causality, our findings support this model and may extend it because TNFαR2, IL-6, and adiponectin remained associated with fatty liver independent of VAT." (PMID 28929125, 2017). "Moreover, the lack of IL-6 predisposes to liver steatosis, thus reinforcing a priori the idea that IL-6 contributes to alleviating steatosis." (PMID 27333268, 2016). "Compared with HFHC, both CAB and HECAB reduced serum insulin and HOMA-IR, attenuated hepatic steatosis, increased SOD1 and CAT, and reduced NF-κB, IL-6, TNF-α, and IL-1β, whereas GPx1 remained unchanged." (PMID 42193214, 2026). "The levels of pro-inflammatory markers, such as IL-6, IL-1β, and TNF-α, were significantly reduced after EA administration, confirming the compound's ability to mitigate hepatic steatosis and inflammation in a dose-responsive manner." (PMID 41530836, 2026). "Collectively, these findings suggest that STING mediates liver steatosis, fibrosis, and inflammation through promoting NF-κB activation and subsequent TNF-α and IL-6 production in KCs." (PMID 40098962, 2025). "Hepatic steatosis and excess visceral adiposity promote the release of pro-inflammatory cytokines—most notably tumor necrosis factor-alpha (TNF-α), interleukin-6 (IL-6), and interleukin-1β (IL-1β)—which exert deleterious effects on musculoskeletal tissues." (PMID 41458554, 2025).
Hepatic steatosis (continued). "Serum fetuin-B has been shown in clinical investigations to be favorably correlated with indicators of adipose tissue inflammation, including IL-6 and TNF-α, as well as the degree of hepatic steatosis." (PMID 40868109, 2025). "There was a significant association between astaxanthin intake and reduced liver fat accumulation, hepatic steatosis, LDL‐C, TG, AST, ALT, IL‐1, TNF‐α, IL‐6, and macrophage inflammatory protein −2 levels." (PMID 40071130, 2025). "The liver communicates with pancreatic β-cells via hepatokines (e.g., fetuin-A, selenoprotein P) and inflammatory cytokines (e.g., IL-6, TNF-α) that are elevated in hepatic steatosis." (PMID 40691629, 2025). "Across studies, key parameters measured include liver steatosis (via histology), serum liver enzymes (ALT/AST), pro-inflammatory cytokines (e.g., TNF-α, IL-6), insulin resistance markers, and gut microbial composition." (PMID 41001122, 2025). "Significantly reduced the fatty liver index, serum GGT and AST values; diminished chronic systemic inflammatory state; and lowered IL-6 and TNF-α concentrations in NAFLD patients." (PMID 38398870, 2024). "Cichoric acid plays an important role in reducing hepatic steatosis, as it reduces the expression of lipogenic actors, such as SREBP-1c, DGAT1, FAS, and SCD-1, and also of inflammatory factors such as IL-6, IL-1b, NF-κB, and TNF-α." (PMID 39458995, 2024). "Acute ethanol-induced hepatic steatosis was alleviated, and the hepatic expression of SREBP-1c and plasma levels of TNF-α, IL-6, and MCP-1 were reduced in fat-1 transgenic mice." (PMID 38791514, 2024). "In ALD cases, hepatic steatosis can lead to concomitant changes in the gene expression levels of proinflammatory factors such as TNF-α, IL-6, and IL-1β." (PMID 38999886, 2024). "In mice with long-term EC-12 consumption, we observed reductions in hepatic steatosis and serum MCP-1 levels and increases in serum IL-6 and IL-10 levels compared to the findings in the control group (Experiment 2)." (PMID 38999780, 2024). "In the humanized liver mouse model, the inflammatory effect of IL-6/GP130 pathway promoted hepatic lipid accumulation, suggesting the therapeutic potential of antagonizing GP130 signaling in the treatment of liver steatosis." (PMID 38890694, 2024). "It was noted that an increased level of liver steatosis showed a significant correlation with a greater abdominal cross-sectional VAT area (cm2) and the HOMA-IR index, along with elevated levels of interleukin 6 (pg/mL) and interleukin 1β (pg/mL)." (PMID 38732626, 2024). "↓BWG, FBG, insulin, HOMA-IR value, serum LPS, hepatic steatosis, adipocyte hypertrophy; ↑HDL-C level; ↓Ileum IL-6 and TNF-α levels; ↑↓Ileum IL-10 levels." (PMID 37396125, 2023). "Meanwhile, in a non-alcoholic fatty liver experimental model, BAs restored the reduced glutathione, and diminished MDA levels and other inflammatory mediators as TNF-α, IL-6, cyclooxygenase 2, and inducible nitric oxide synthase in hepatic tissues." (PMID 36959348, 2023). "As demonstrated in previous studies, IL-6 and TNF-α are significant cytokines in the development of hepatic steatosis." (PMID 38116565, 2023). "EMPA mitigated the hepatic content of TNF-α, IL-6, and NFκB in a dose-dependent manner that aligns with previous in vitro and in vivo investigations, in which EMPA lessens hepatic steatosis." (PMID 36358524, 2022). "Hepatic steatosis and the resulting NAFLD can lead to additional chronic inflammation by secretion of inflammatory cytokines such as IL6, TNF-alpha, and leptin." (PMID 35407455, 2022). "Here, we provide solid evidence that celecoxib reduces lipogenesis‐triggered hepatic steatosis in AKT‐transfected mice, accompanied by the suppression of hepatocellular inflammatory responses (TNF‐α, IL‐6 and IL‐1β)." (PMID 35713152, 2022).